CT45A3 (cancer/testis antigen family 45 member A3)
Synonyms: CT45-3; CT45-4; CT45A4; CT45.3; CT45.4
Tractability: PROTAC: ubiquitination databases record sites on it.
Gene: Protein-coding gene on chromosome X (135,759,846 to 135,768,191, reverse strand). Ensembl gene ENSG00000269096.
Subcellular location: Nucleus
Subcellular location (Human Protein Atlas): Nucleoli; Nucleoplasm
Gene Ontology:
Molecular function: protein binding
Cellular component: nucleus
Homologues: Orthologues: rat Ct45a9 (29% identical), mouse Ct45a (28% identical), Caenorhabditis elegans ints-6 (17% identical), Drosophila melanogaster IntS6 (16% identical). Paralogues in human: CT45A1 (99% identical), CT45A5 (99% identical), CT45A6 (99% identical), CT45A7 (99% identical), CT45A2 (98% identical), CT45A8 (98% identical), CT45A9 (98% identical), CT45A10 (94% identical), SAGE1 (35% identical), INTS6L (31% identical), INTS6 (25% identical).
Diseases named in the same sentence as CT45A3 in open-access papers:
CT45A3 is named in the same sentence as 5 diseases in open-access papers, as found by Europe PMC text mining. Sharing a sentence is not in itself a finding about the gene and the disease. The quoted sentences say what the papers report.
ovarian carcinoma (1 paper, 2025). A malignant neoplasm originating from the surface ovarian epithelium. "High expression of CT45A3 has been associated with disease progression and poor prognosis in ovarian cancer." (PMID 40136427, 2025).
cancer (4 papers, 2012 to 2025). A tumor composed of atypical neoplastic, often pleomorphic cells that invade other tissues. "Examples of biclusters from this category include the biclusters consisting of genes from the Cancer-Testis antigens family—MAGEA2, MAGEA3, MAGEA6, MAGEA10, CSAG1, CSAG2, CSAG3 (Xq28)/CT45A3, CT45A5, CT45A6 (Xq26.3)." (PMID 31216036, 2019). "Not surprisingly, several cancer testis antigens (CTA) including CT45A1, CT45A3, CT45A5, CTAG1B and CTAG2 were highly expressed in TNB-High or TMB-High tumors." (PMID 41562064, 2025).
tumor (1 paper, 2025). "Additionally, the expression of tumor-associated genes such as CT45A3, TPBG, HOXA4, ZNF185, and SNX19 was significantly downregulated." (PMID 40136427, 2025). "The decrease in the expression of CT45A3 following EPZ004777 treatment could suggest that the tumor progression could be impeded by the treatment." (PMID 40136427, 2025).
CT45A3 also shares sentences with these, for which no sentence is quoted: HIV-1 infection (1 paper); infection (1).